MLKL (mixed lineage kinase domain like pseudokinase)
Description:
Pseudokinase that plays a key role in TNF-induced necroptosis, a programmed cell death process. Does not have protein kinase activity. Activated following phosphorylation by RIPK3, leading to homotrimerization, localization to the plasma membrane and execution of programmed necrosis characterized by calcium influx and plasma membrane damage. In addition to TNF-induced necroptosis, necroptosis can also take place in the nucleus in response to orthomyxoviruses infection: following activation by ZBP1, MLKL is phosphorylated by RIPK3 in the nucleus, triggering disruption of the nuclear envelope and leakage of cellular DNA into the cytosol.following ZBP1 activation, which senses double-stranded Z-RNA structures, nuclear RIPK3 catalyzes phosphorylation and activation of MLKL, promoting disruption of the nuclear envelope and leakage of cellular DNA into the cytosol (By similarity). Binds to highly phosphorylated inositol phosphates such as inositolhexakisphosphate (InsP6) which is essential for its necroptotic function.
Synonyms: hMLKL; FLJ34389
Tractability: Small molecule: a structure with a bound ligand is known; a high-quality ligand is known; it belongs to a druggable protein family. Antibody: UniProt places it where antibodies can reach, with high confidence; its Gene Ontology location is reachable by antibodies, with high confidence; the Human Protein Atlas places it where antibodies can reach. PROTAC: ubiquitination databases record sites on it; its protein half-life has been measured; a small molecule that binds it is known.
Chemical probes: BI-8925 (high quality)
Gene: Protein-coding gene on chromosome 16 (74,671,855 to 74,701,156, reverse strand). Ensembl gene ENSG00000168404.
Subcellular location: Cytoplasm; Cell membrane; Nucleus
Subcellular location (Human Protein Atlas): Plasma membrane; Cell Junctions; Cytosol
Pathways (Reactome):
Disease: Microbial modulation of RIPK1-mediated regulated necrosis; NS1 Mediated Effects on Host Pathways
Programmed Cell Death: RIPK1-mediated regulated necrosis; Regulation of necroptotic cell death
Transport of small molecules: TRP channels
Gene Ontology:
Molecular function: ATP binding; protein binding; protein-containing complex binding; protein kinase activity; protein serine/threonine kinase activity; protein kinase binding
Biological process: execution phase of necroptosis; necroptotic process; necroptotic signaling pathway; protein homotrimerization; defense response to virus; cell surface receptor signaling pathway
Cellular component: cell junction; cytoplasm; cytosol; plasma membrane; nucleus
Genetic constraint (gnomAD): Loss-of-function variants: 54 observed, 56.75 expected, observed/expected ratio (o/e) 0.95, 90% interval 0.76 to 1.19. The upper end of that interval is the gene's LOEUF score, 1.19, which puts it in group 5 of 6, group 1 being the genes least tolerant of losing a copy. Missense variants: 686 observed, 597.13 expected, observed/expected ratio (o/e) 1.15, 90% interval 1.08 to 1.22. Synonymous variants: 248 observed, 219.84 expected, observed/expected ratio (o/e) 1.13, 90% interval 1.02 to 1.25.
Homologues: Orthologues: chimpanzee MLKL (98% identical), macaque MLKL (90% identical), pig MLKL (63% identical), rat Mlkl (62% identical), mouse Mlkl (61% identical), guinea pig MLKL (52% identical), tropical clawed frog mlkl (34% identical). Paralogues in human: LIMK1 (18% identical), LIMK2 (17% identical), RAF1 (17% identical), LRRK2 (17% identical), MAP3K9 (17% identical), BRAF (16% identical), MAP3K11 (16% identical), TESK1 (16% identical), MAP3K10 (15% identical), TESK2 (15% identical), TNNI3K (15% identical), KSR1 (15% identical), and 11 more.
Diseases named in the same sentence as MLKL in open-access papers:
MLKL is named in the same sentence as 295 diseases in open-access papers, as found by Europe PMC text mining. Sharing a sentence is not in itself a finding about the gene and the disease. The quoted sentences say what the papers report.
colitis (34 papers, 2017 to 2025). Inflammation of the colon. "RIPK3 and MLKL deficiency was reported to inhibit DSS-induced colitis, and MLKL or the RIPK3/necroptosis axis is a driving force for intestinal inflammation." (PMID 40877233, 2025). "challenged these results in their report showing that germline deficiency of MLKL or RIPK3 exacerbates the severity of DSS-induced colitis." (PMID 37409125, 2023). "In the meantime, the survival curve demonstrated that RIPK3-/- and MLKL-/- mice were susceptible to DSS-induced colitis." (PMID 37691056, 2023). "We previously reported that the loss of MLKL led to increased susceptibility to colitis-associated tumorigenesis." (PMID 33767595, 2021). "Mice with IEC-specific FADD or caspase-8 deficiency develop colitis depending on MLKL-mediated epithelial cell necroptosis." (PMID 33050394, 2020). "MLKL-/- mice are highly susceptible to colitis and colitis-associated tumorigenesis, associated with massive leukocyte infiltration and increased inflammatory responses, suggesting a protective role of the necroptosis effector." (PMID 33050394, 2020). "In this study, we found that p-MLKL was significantly increased in colons of mice with DSS-induced colitis and that MLKL deficiency completely protected mice against DSS-induced colitis." (PMID 31019191, 2019). "To further identify the contribution of necroptosis in ΔsopB mediated increased severity to colitis, we employed MLKL deficient mice." (PMID 31024858, 2019). "Moreover, in vivo, we found that inhibition of RIPK3 or MLKL pharmacologically completely rescued DJ-1 deficiency-related colitis." (PMID 40877233, 2025). "However, we noted an elevation in p-MLKL levels in CAV1-deficient colitis mice, suggesting a potential link between CAV1-induced epithelial demise and necroptosis." (PMID 40877233, 2025). "For example, Karki study showed that knockdown of interferon regulatory factor 1 could significantly inhibit the activation of GSDMD (pyroptosis), CASP3/7 (apoptosis) and MLKL (necroptosis), thereby promoting cell death in colitis-associated CRC." (PMID 39331898, 2024). "Furthermore, MLKL is a crucial mediator of necrosis, leading to the release of cell DAMPs, and mlkl−/− mice are susceptible to colitis and colitis-associated tumorigenesis." (PMID 37238692, 2023). "Moreover, HSD was shown to significantly promot the IBD process in vivo and mice with genetic deletion of RIPK3/MLKL was susceptible to DSS-induced colitis." (PMID 37691056, 2023). "Genetic deletion of RIPK3 or MLKL was susceptible to DSS-induced colitis in vivo." (PMID 37691056, 2023). "Recently, we reported that loss of MLKL accelerated colitis-associated tumorigenesis." (PMID 33767595, 2021). "Moreover, loss of MLKL also prevents dextran sodium sulfate (DSS)-induced colitis." (PMID 39118979, 2024). "The severity of inflammation in experimental colitis was found to be exacerbated by a defect in either RIPK3 or MLKL, leading to necroptosis." (PMID 40877233, 2025). "Conversely, supplementation of GSK872 remarkably suppressed the phosphorylation of RIPK3 and MLKL in CKO T cells during colitis." (PMID 36721037, 2023). "The important role of MLKL in this disease scenario is further supported by recent observations that MLKL fully mediates the ileitis and colitis observed in mice with intestinal epithelial cell-specific deficiency of Caspase-8." (PMID 35166320, 2022). "Hesperetin, a flavonoid from citrus fruits inactivates RIPK3/MLKL signaling improving the DSS-induced colitis in mice." (PMID 33050394, 2020). "Collectively, these data indicated that MLKL mediated necroptosis contributes to the increased severity to colitis in mice infected with ΔsopB." (PMID 31024858, 2019). "We found SopB deletion upregulated MLKL phosphorylation which increased cell necroptosis and consequently increased severity to colitis and promotes bacterial translocation." (PMID 31024858, 2019).
colitis (continued). "Conclusively, these results suggested that MLKL plays an indispensable role for protection against Salmonella-induced colitis." (PMID 29456533, 2018). "Our results support that IPA, a bacterial metabolite, may block the epithelial necroptosis by inhibiting the RIPK1/RIPK3/MLKL pathway, which may give a rational explanation for the lower concentration of its in both colonic tissue and serum of colitis." (PMID 40745657, 2025). "In addition, in DSS-induced colitis, the DJ-1 deficiency-induced activation of p-RIPK1, p-RIPK3 and p-MLKL was dramatically blunted in the DKO mice." (PMID 40877233, 2025). "Importantly, MLKL co-deletion can completely prevent colitis while ileitis is only completely prevented by co-deletion of MLKL in FaddIEC-KO; Casp8IEC-KO." (PMID 38783091, 2024). "In this study, the protein expression levels of RIP1, RIP3, and MLKL in mice with DSS-induced colitis were significantly higher than in the control mice, and the rectal administration of PA/CCMTS-P could significantly reverse this phenotype." (PMID 36843930, 2023). "Recently, a newly published study found MLKL deficiency has a little effect on intestinal microbiota composition which did not affect severity to DSS induced colitis." (PMID 31024858, 2019). "Intriguingly, MLKL deletion rescued severity to ΔsopB induced colitis." (PMID 31024858, 2019). "Furthermore, MLKL attenuated colon inflammation and colitis tumorigenesis via suppression of inflammatory responses, inhibited intestinal tumorigenesis by suppressing the IL-6/JAK2/STAT3 pathway and promoted cellular differentiation in myeloid leukemia by facilitating the release of G-CSF." (PMID 36828808, 2023). "To verify the clinical value of CAV1 and necroptosis in colitis, we collected intestinal samples from IBD patients and observed that CAV1 and p-MLKL were both significantly increased in advanced UC and CD patients compared with healthy controls." (PMID 40877233, 2025). "The activation of the RIPK3/MLKL pathway has been well-confirmed in human IBD and murine model of colitis." (PMID 40745657, 2025). "In the same way, celastrol administration has been found to relieve the severity of colitis by decreasing IL-1β, IL-6, myeloperoxidase (MPO), RIPK3, and MLKL levels while increasing active caspase-8 levels and E-cadherin." (PMID 39118979, 2024). "Some studies have investigated the potential involvement of necroptosis using the pharmacological inhibitor of MLKL, necrosulfonamide (NSA), in the 2,4,6-trinitrobenzenesulfonic acid (TNBS)-induced mouse model of colitis." (PMID 37409125, 2023). "In colitis model, we determined an inhibition of RIPK3 and MLKL during necroptosis in the inflamed epithelium, whereas a down-regulation of RIPK3 and MLKL was observed in the M10-treated epithelium." (PMID 33041798, 2020). "Indeed, CRIF1 overexpression reduced the numbers of cells expressing TNF-α, TNFR1, RIPK1, RIPK3, and phosphorylated MLKL in our experimental mice, suggesting that CRIF1 overexpression can downregulate intestinal inflammatory cell death in colitis." (PMID 40821844, 2025). "Moreover, hesperetin has been demonstrated to greatly lessen the manifestations of DSS-induced colitis, suppress RIPK3 and MLKL expression, and deactivate their necroptosis signaling pathways." (PMID 39118979, 2024). "In addition, recent study found that NSA inhibited phosphorylated MLKL and N-GSDMD expression in dextran sodium sulfate-induced colitis mouse model, inhibited N-GSDMD expression in bone marrow-derived macrophages and phosphorylated MLKL in NCM460 cells." (PMID 38129399, 2023). "Supposedly, polysaccharides from edible mushrooms inhibit colitis, and polysaccharide extracts significantly inhibit the receptor-interacting protein kinase RIPK1–RIPK3–MLKL necroptotic signaling cascade, thereby decreasing the levels of phosphorylated MLKL in the mouse colon." (PMID 37238692, 2023).
colitis (continued). "In conclusion, our study shows that curcumin has a positive role in colitis-induced intestinal epithelial injury by inhibiting the expression of p-RIP3 and p-MLKL by targeting RIP3, decreasing inflammatory cytokines expression, and inducing intestinal epithelial barrier integrity." (PMID 37089942, 2023). "We found that ABIN1, RIPK1, RIPK3, and MLKL were upregulated in UC sample and DSS-induced colitis." (PMID 36034412, 2022). "Mice lacking intestinal epithelial cell (IEC) caspase-8 develop colitis and ileitis which can be rescued by deletion of MLKL." (PMID 35563804, 2022). "We found that ABIN1, RIPK1, RIPK3, and MLKL were upregulated in UC samples and DSS-induced colitis." (PMID 36034412, 2022). "Although MLKL-mediated necroptosis is involved in host defense to microbial infection, the biological implications of MLKL in bacterially triggered colitis have not been characterized." (PMID 29456533, 2018). "The increased colonic inflammation and the resistance to colitis were restored by dual inactivation of RIPK3 and FADD, but not by inhibition of RIPK3, MLKL, or ZBP1 alone." (PMID 34462571, 2022). "Colitis and ileitis also occur in mice lacking FADD in IECs, with cell death mediated by MLKL and caspase-8-dependent activation of GSDMD." (PMID 35563804, 2022). "Because NSA targets the Cys86 residue of human MLKL and not mouse MLKL, we did not test protective effect of NSA against TNBS-induced colitis in mice; hence, we explored the protective effect of NSA on Caco-2 cells in a novel in vitro model of necroptosis." (PMID 29156831, 2017). "The results showed that RI-962 reduced the levels of pRIPK1, pRIPK3, and pMLKL proteins in the colon during DSS challenge, but did not impact the expression of RIPK1, RIPK3, and MLKL proteins, suggesting that RI-962 suppressed the RIPK1 signaling in the mouse model of DSS-induced colitis." (PMID 36371441, 2022). "In the colons of DSS-treated mice, p-MLKL was increased on day 7 and day 10, but little cleaved caspase-3 was detected, suggesting that necroptosis, but not apoptosis, contributed to DSS-induced colitis." (PMID 31019191, 2019).
breast carcinoma (33 papers, 2016 to 2026). "Nevertheless, Cdc42 (together with Rac1) plays a role at least in the DF variant-promoted activation of MLKL in the T-47D breast cancer cells." (PMID 39062543, 2024). "All of these data clearly indicate that the DS variants promote their activating effect on MLKL by inducing transient oxidative stress in luminal breast cancer cells." (PMID 39062543, 2024). "Thus, we used this approach to quantify the activation of MLKL in the breast cancer cultures that had been exposed to the tested DS variants for 3.5 h in order to investigate the intracellular events leading to this process." (PMID 39062543, 2024). "As the activation of MLKL is associated with its phosphorylation by RIPK3, the effect of DS variants on the phospho-MLKL level in breast cancer cells might probably be mediated through the stimulatory impact of these glycans on the kinase activity." (PMID 39062543, 2024). "Our data clearly indicate that the DS variant-induced redox imbalance is an event upstream of the MLKL activation that was promoted by these molecules in luminal breast cancer cells, although the involvement of oxidized RIPK1 in this process remains unknown." (PMID 39062543, 2024). "All of the current and previous data clearly showed that an immunofluorescence analysis of the DS variant-induced activation of MLKL in luminal breast cancer cells, although less sensitive than Western blotting, can be used to assess the quantitative effects that are triggered by these glycans." (PMID 39062543, 2024). "In order to further corroborate this hypothesis, we examined the presence of activated MLKL oligomers in the breast cancer cells that had been exposed to the DS variants for three time periods." (PMID 35011734, 2022). "Since necroptosis is pro-inflammatory cell death, the production of inflammatory cytokines was significantly reduced in macrophages of MLKL-deficient tumors, suggesting that the inflammatory response induced by necroptosis may contribute to breast cancer lung metastasis." (PMID 36675706, 2022). "Although phosphorylated MLKL (p-MLKL) detection via immunohistochemistry has been reported in various human cancers (e.g., colorectal and breast carcinomas) as a surrogate readout for necroptosis, its specificity and reliability remain challenged." (PMID 41334873, 2025). "Clinical studies also reveal that RIPK1 and MLKL mRNA expression levels exhibit a significant downward trend in breast cancer tissues, potentially increasing intrinsic resistance to lethal signals and enabling evasion of immune surveillance." (PMID 41334873, 2025). "For MLKL gene expression, IFNγ upregulates MLKL mRNA in breast carcinoma and cervical carcinoma cells, and IRF1 or STAT1 knockout reverses IFNγ-mediated induction of the MLKL mRNA level." (PMID 38671928, 2024). "The current investigation using these variants clearly indicates that the two intracellular events that are triggered by them in luminal breast cancer cells are principally responsible for the ability of these molecules to induce MLKL phosphorylation." (PMID 39062543, 2024). "IFN signaling induces MLKL mRNA and protein expression in breast carcinoma and Hela carcinoma cells." (PMID 39457421, 2024). "A recent study used phosphorylated MLKL-specific antibodies to detect necrotizing apoptosis of tumor cells occurring in mouse models of breast cancer MMVT-PyMT." (PMID 38546403, 2024). "The combined administration of cardamonin and PM triggered an increase in the level of phospho-MLKL in both breast cancer lines compared not only to the corresponding control but also to the parallel cultures that had been treated with the variant alone." (PMID 39062543, 2024). "In human breast cancer, it has been shown that necrosis can occur through finely tuned regulation of a series of pro-necrotic genes including MLKL, RIPK1, RIPK3, PGAM5, and DFNA520." (PMID 38773214, 2024).